OR51S1 (olfactory receptor family 51 subfamily S member 1)
Description:
Odorant receptor.
Synonyms: OR11-24
Tractability: Antibody: UniProt places it where antibodies can reach, with medium confidence; UniProt predicts a signal peptide or a membrane-spanning region; its Gene Ontology location is reachable by antibodies, with medium confidence.
Gene: Protein-coding gene on chromosome 11 (4,848,237 to 4,849,208, reverse strand). Ensembl gene ENSG00000176922.
Subcellular location: Cell membrane
Pathways (Reactome):
Sensory Perception: Expression and translocation of olfactory receptors
Gene Ontology:
Molecular function: olfactory receptor activity; G protein-coupled receptor activity
Biological process: detection of chemical stimulus involved in sensory perception of smell; G protein-coupled receptor signaling pathway
Cellular component: plasma membrane; membrane
Genetic constraint (gnomAD): Loss-of-function variants: 1 observed, 1.93 expected, observed/expected ratio (o/e) 0.52, 90% interval 0.17 to 1.76. That is too few expected variants to judge how well the gene tolerates losing a copy. Missense variants: 479 observed, 414.98 expected, observed/expected ratio (o/e) 1.15, 90% interval 1.07 to 1.25. Synonymous variants: 180 observed, 167.25 expected, observed/expected ratio (o/e) 1.08, 90% interval 0.95 to 1.22.
Homologues: Orthologues: chimpanzee OR51S1 (99% identical), macaque OR51S1 (92% identical), dog OR51S1 (83% identical), pig OR51S1 (81% identical), mouse Or51s1 (80% identical), rat Or51s1 (79% identical). Paralogues in human: OR51G1 (42% identical), OR51G2 (42% identical), OR51A4 (42% identical), OR51A2 (42% identical), OR51A7 (42% identical), OR51I2 (41% identical), OR51E1 (41% identical), OR51B5 (41% identical), OR51L1 (40% identical), OR52K2 (40% identical), OR52D1 (40% identical), OR52L1 (40% identical), and 39 more.